CKAP2 (cytoskeleton associated protein 2)
Description:
Possesses microtubule stabilizing properties.
Synonyms: LB1; TMAP; FLJ10749; se20-10
Tractability: PROTAC: ubiquitination databases record sites on it; its protein half-life has been measured.
Gene: Protein-coding gene on chromosome 13 (52,455,429 to 52,476,630, forward strand). Ensembl gene ENSG00000136108.
Subcellular location: Cytoplasm, cytoskeleton; Cytoplasm, cytoskeleton, spindle; Cytoplasm, cytoskeleton, spindle pole
Subcellular location (Human Protein Atlas): Microtubules; Mitotic spindle; Primary cilium; Basal body; Centrosome
Gene Ontology:
Biological process: mitotic cytokinesis; positive regulation of transcription by RNA polymerase II; negative regulation of microtubule depolymerization
Cellular component: centrosome; ciliary basal body; cilium; microtubule cytoskeleton; mitotic spindle; cytoskeleton; spindle; spindle pole
Genetic constraint (gnomAD): Loss-of-function variants: 40 observed, 52.98 expected, observed/expected ratio (o/e) 0.76, 90% interval 0.58 to 0.98. The upper end of that interval is the gene's LOEUF score, 0.98, which puts it in group 4 of 6, group 1 being the genes least tolerant of losing a copy. Missense variants: 751 observed, 786.04 expected, observed/expected ratio (o/e) 0.96, 90% interval 0.9 to 1.01. Synonymous variants: 276 observed, 283.18 expected, observed/expected ratio (o/e) 0.97, 90% interval 0.88 to 1.08.
Homologues: Orthologues: chimpanzee CKAP2 (98% identical), macaque CKAP2 (95% identical), rabbit CKAP2 (77% identical), pig CKAP2 (76% identical), dog CKAP2 (70% identical), guinea pig CKAP2 (61% identical), mouse Ckap2 (60% identical), rat Ckap2 (60% identical), tropical clawed frog ckap2 (32% identical), zebrafish si:ch211-266i6.3 (18% identical). Paralogues in human: CKAP2L (23% identical).
Diseases named in the same sentence as CKAP2 in open-access papers:
CKAP2 is named in the same sentence as 49 diseases in open-access papers, as found by Europe PMC text mining. Sharing a sentence is not in itself a finding about the gene and the disease. The quoted sentences say what the papers report.
breast carcinoma (14 papers, 2014 to 2025). "LncRNAs such as lymphocytic leukemia 1 (DLEU1) are associated with breast cancer and up-regulate CKAP2 expression to promote breast cancer malignancy via serving as a co-activator of HIF-1α." (PMID 36597032, 2023). "This study not only corroborates the oncogenic roles of DLEU1, HIF-1α, and CKAP2, but also justifies the potential of targeting these molecules in the treatment of breast cancers, particularly those associated with higher malignancy and worse prognosis." (PMID 35853854, 2022). "On the molecular level, we detected the significant increases of CKAP2 protein and mRNA expression in DLEU1-overexpressing MCF7 cells, supporting the association between DLEU1-induced up-regulation of CKAP2 and the enhanced malignancy of breast cancer cells." (PMID 35853854, 2022). "CKAP2, a microtubule-associated protein and a critical regulator of cell division, has been well demonstrated to as an oncogene in different cancers, such as ovarian cancer, breast cancer, osteosarcoma, glioma, cervical cancer, and gastric cancer." (PMID 35853854, 2022). "In cluster 1, breast cancer cell markers, including Nob1, Vmp1, Crk, Ckap2, Parp14 and Mfn1, were detected among the top cluster markers." (PMID 39054536, 2024). "LncRNA DLEU1 (deleted in lymphocytic leukemia 1) acts as the coactivator for hypoxia inducible factor 1 subunit alpha (HIF-1α) to induce expression of cytoskeleton associated protein 2 (CKAP2) and consequently pro-tumor activities in breast cancer." (PMID 39346726, 2024). "We demonstrated the direct interaction between DLEU1 and HIF-1α in breast cancer cells, the impact of knocking down each on the expression of CKAP2, and their separate yet positive correlation with CKAP2 level in breast cancer." (PMID 35853854, 2022). "In breast cancer, CKAP2 is revealed as a biomarker for proliferation and an independent prognostic indicator." (PMID 35853854, 2022). "In this study, we detected the alterations in ERK1/2 and STAT3 activation when CKAP2 level was changed in breast cancer cells, suggesting the potential involvement of these two signaling pathways, which awaits detailed characterization in future studies." (PMID 35853854, 2022). "In summary, here we present seminal findings that DLEU1, by activating HIF-1α-induced transcription of CKAP2, promotes malignant growth and metastatic spread of breast cancer." (PMID 35853854, 2022). "We found that CKAP2 expression presented a positive correlation with DLEU1 in breast cancer tissues (n = 1104), implying a potential regulation between these two molecules, which has not been reported." (PMID 35853854, 2022). "Recent studies suggest that CKAP2 is up-regulated and contributes to the malignant progression of diverse human cancers, including breast cancer." (PMID 35853854, 2022). "In particular, CKAP2 is up-regulated in glioma, osteosarcoma, breast cancer, and cervical cancer and engaged in their progression." (PMID 34596006, 2021). "Chromatin CKAP2 staining was evident in mitotic cells, and the number of chromatin CKAP2-positive cells were variable among breast cancer cases." (PMID 28771517, 2017). "Another recent study has identified CKAP2 as a prognostic marker for relapse-free survival in early-stage breast cancer." (PMID 27341628, 2016). "Immunohistochemical staining in normal breast tissues adjacent to cancer cells revealed rare CKAP2 staining, but in breast cancer tissues, CKAP2 was localized in the condensed chromatin of the mitotic cells (arrows)." (PMID 24887265, 2014). "In summary, the present study has shown that chromatin CKAP2 is an effective independent prognostic marker for RFS in early-stage breast cancer." (PMID 24887265, 2014). "Further investigation of chromatin CKAP2’s clinical application to the management of breast cancer treatment, therefore, is warranted." (PMID 24887265, 2014).
breast carcinoma (continued). "As the present study has confirmed the significant correlation of a new proliferation marker, the CPCC, with RFS, further studies on chromatin CKAP2 as a possible prognostic or predictive marker in the management of breast cancer are warranted." (PMID 24887265, 2014). "Previous studies have shown that CKAP2 expression is elevated in various cancers, including gastric adenocarcinoma, lung adenocarcinoma, hepatocellular carcinoma, cervical carcinoma, and breast carcinoma, where it influences tumor cell proliferation, migration and invasion." (PMID 40636121, 2025). "The biological mechanisms of CKAP2 affecting the development of breast cancer, gastric cancer, and ovarian cancer have been probed, but the expression and role of CKAP2 in CRC remain unclear." (PMID 39403723, 2024). "To test this hypothesis, we explored the interactions between DLEU1, HIF-1α, and CKAP2 in breast cancer tissues acquired from patients or database, in breast cancer cells cultured in vitro, and in in vivo xenografts or metastasis models." (PMID 35853854, 2022). "Therefore, DLEU1, by acting as a coactivator for HIF-1α, up-regulates CKAP2 expression and promotes malignancy of breast cancer." (PMID 35853854, 2022). "Therefore, clinical significance of CKAP2 was evaluated in comparison with that of Ki-67 in a cohort of breast cancer patients, and the expression difference was analyzed in cell cycle-arrested cancer and fibroblast cells." (PMID 28771517, 2017). "Chromatin CKAP2 is an independent prognostic marker for RFS in early-stage breast cancer, and could potentially replace the MAI in clinical evaluation of proliferation activity." (PMID 24887265, 2014). "The numbers of chromatin-stained CKAP2-positive cells varied according to the breast cancer cases." (PMID 24887265, 2014). "The present study by means of an immunohistochemical evaluation of chromatin CKAP2-positive cell counts, showed that breast cancer with higher CPCC values was significantly correlated with worse RFS in the multivariate analyses across two independent institutions." (PMID 24887265, 2014). "Targeting DLEU1, HIF-1α, or CKAP2 may thus benefit breast cancer treatment." (PMID 35853854, 2022). "As the use of IHC markers offers great potential advantages in regard to evaluation time and efficiency, CKAP2 immunohistochemistry could facilitate the clinical application of proliferation activity to breast cancer by providing a simple and effective MAI-alternative measure." (PMID 24887265, 2014). "TCGA analysis of 1104 breast cancer samples showed a significant positive correlation between HIF-1α and CKAP2 expression levels." (PMID 35853854, 2022). "In order to determine whether CKAP2 overexpression in invasive BC can be recapitulated in another continuous model of BC, we took advantage of the MCF10A breast cancer cell line series, a powerful cell culture model system for studying BC evolution." (PMID 35954424, 2022). "CKAP2, a major member of CKAP, serves as a marker of breast cancer proliferation and an independent predictor of its prognosis, as reported." (PMID 34596006, 2021). "The current evidence indicates that CKAP2 is not likely to be a favorable prognostic factor in glioma, breast cancer, and ovarian cancer." (PMID 36699449, 2022). "Therefore, in the present study, the prognostic significance of chromatin CKAP2 was evaluated in 375 early-stage breast cancer cases, from two independent institutions, as based on the CPCC in CKAP2 immunohistochemistry." (PMID 24887265, 2014). "Since CKAP2 appears to be more specific to actively proliferating cells, CPCC could be an alternative option or a complementary to Ki-67LI or MAI as a prognostic marker in breast cancer." (PMID 28771517, 2017). "Thus, a proliferation marker, chromatin CKAP2, might be a new useful and alternative prognostic tool to the MAI in breast cancer." (PMID 24887265, 2014).
gastric cancer (10 papers, 2013 to 2026). A primary or metastatic malignant neoplasm involving the stomach. "CKAP2 is up-regulated in a variety of malignant tumors and has diagnostic value in osteosarcoma, triple-negative breast cancer, gastric cancer, and other tumors." (PMID 38558817, 2024). "CKAP2 expression is proved to be upregulated in diverse malignant tumors, such as gastric cancer, lung adenocarcinoma, and skin T-cell lymphoma [17, -19]." (PMID 39403723, 2024). "CKAP2 gene expression is frequently upregulated in various malignancies, such as gastric cancer, ovarian cancer, glioma, and lymphoma, although little is known about its role in BC." (PMID 35954424, 2022). "Cytoskeleton-associated protein 2 (CKAP2), also known as tumor-associated microtubule-associated protein (TMAP), is frequently upregulated in various malignancies, including stomach cancer and diffuse large B-cell lymphoma." (PMID 23737987, 2013). "Because cytoskeleton-associated protein 2 (CKAP2) staining has recently been introduced as a marker of proliferation activity, we analyzed 437 gastric cancer tissues through CKAP2 immunohistochemistry, and we evaluated the chromatin CKAP2-positive cell count (CPCC) for proliferation activity." (PMID 26542785, 2015).
ovarian carcinoma (9 papers, 2021 to 2025). A malignant neoplasm originating from the surface ovarian epithelium. "CKAP2 is involved in ovarian cancer tumorigenesis through FAK-ERK pathway and a potential prognostic marker of HER2-negative luminal type breast cancer." (PMID 33846420, 2021). "Interestingly, previous findings have confirmed CKAP2’s carcinogenic effects on ovarian cancer and cervical cancer by activating the FAK-ERK pathway." (PMID 34596006, 2021). "Furthermore, CKAP2 acts as a significant paralog of CKAP2L, and the oncogenic nature and overexpression of this gene is revealed in PCa, ovarian cancer, and glioma." (PMID 33927744, 2021).
hepatocellular carcinoma (7 papers, 2017 to 2025). A malignant tumor that arises from hepatocytes. "This regulatory mechanism of miR-3200-5p is competitively inhibited by DARS-AS1 and targets the cytoskeleton-associated protein 2 (CKAP2) to aggravate the growth and invasion of hepatocellular carcinoma." (PMID 35615577, 2022). "DARS-AS1 could facilitate the viability and metastasis of hepatocellular carcinoma by adjusting miR-3200-5p-mediated CKAP2." (PMID 36568518, 2022).
glioma (6 papers, 2020 to 2025). A benign or malignant brain and spinal cord tumor that arises from glial cells (astrocytes, oligodendrocytes, ependymal cells). "For example, Wang and colleagues found that the silencing of CKAP2 by siRNA suppressed the proliferative capacity and clonogenicity of glioma cells." (PMID 35954424, 2022). "CKAP2 gene is also upregulated in various kinds of cancer, including breast, prostate, stomach, and ovarian cancers, as well as glioma." (PMID 33375517, 2020). "Previous studies proved that CKAP2 could promote the progression of triple-negative breast cancer, high−grade glioma, etc., while there is still a lack of evidence in lung cancer." (PMID 39949782, 2025).
osteosarcoma (6 papers, 2013 to 2025). A usually aggressive malignant bone-forming mesenchymal neoplasm, predominantly affecting adolescents and young adults. "Additionally, Zhang and colleagues found that the CKAP2 knockdown by shRNA impaired osteosarcoma cell growth in vivo and in vitro." (PMID 35954424, 2022).
cervical carcinoma (5 papers, 2017 to 2025). A carcinoma arising from either the exocervical squamous epithelium or the endocervical glandular epithelium. "In order to probe the CKAP2-associated pathways in cervical carcinoma, we first performed GSEA using high throughput RNA-sequencing data of the cervical carcinoma tumors of TCGA database." (PMID 28522860, 2017). "In conclusion, the present study, for the first time, suggests that CKAP2 acts as a functional oncogene in cervical carcinoma cell line, and the upregulation of CKAP2 expression is closely associated with cervical carcinoma cell proliferation and motility through FAK-ERK2 signaling pathway." (PMID 28522860, 2017). "HeLa and C-33A cells showed higher CKAP2 expression, and SiHa cells showed lowest expression of CKAP2 compared with other cervical carcinoma cell lines." (PMID 28522860, 2017). "In the present study, we screened CKAP2 as a new candidate gene which promotes development of cervical carcinoma, in two independent datasets (TCGA and GSE27678)." (PMID 28522860, 2017). "Meanwhile, Real-time PCR also showed upregulated CKAP2 expression in cervical carcinoma tissues when compared with the adjacent tissues of patients in Obstetrics and Gynecology Hospital, Fudan University." (PMID 28522860, 2017). "Next, we also detected the expression of CKAP2 in cervical carcinoma cell lines, including C-33A, CaSki, HeLa, SiHa and C4-1, in both mRNA and protein levels." (PMID 28522860, 2017). "High expression of CKAP2 was observed in human cervical carcinoma tissues compared with adjacent tissues." (PMID 28522860, 2017). "In line with the previous studies, more importantly in our study, the migration and invasion ability of cervical carcinoma cells was increased after CKAP2 overexpression, but was inhibited by either PF-562271 or VX-11e treatment." (PMID 28522860, 2017). "Bioinformatics analysis was used to measure CKAP2 expression in cervical carcinoma tissues and adjacent normal counterparts." (PMID 28522860, 2017). "To assess the biological role of CKAP2 in cervical carcinoma cells, we investigated the effects of targeted knockdown of CKAP2 on cell proliferation." (PMID 28522860, 2017). "In the current study, we showed that the expression level of CKAP2 was higher in cervical carcinomas tissues than in adjacent tissues." (PMID 28522860, 2017). "The survival time of cervical carcinoma patients showed that patients with under-expressed CKAP2 expression notably lived longer than patients with over-expressed CKAP2 expression." (PMID 28522860, 2017). "In the present study, we found that CKAP2 was upregulated in cervical carcinoma and HPV-16-positive CIN III tissues compared with either adjacent tissues or nontumor tissues both in mRNA and/or protein levels." (PMID 28522860, 2017). "The expression of CKAP2 was significantly upregulated in cervical carcinoma tissues when compared with the adjacent or normal counterparts in the TCGA data and GSE27678 database." (PMID 28522860, 2017). "We also showed that knockdown of CKAP2 inhibited the proliferation, migration and invasion of cervical carcinomas cells." (PMID 28522860, 2017). "Taken together, these results suggest that CKAP2 could regulate cervical carcinogenesis and may serve as a potential target for cervical carcinomas therapies." (PMID 28522860, 2017). "Then we detected the clinical relevance of CKAP2 expression in cervical carcinoma, of the 247 human cervical carcinoma tissues were further classified into the high-CKAP2 group (n = 125) and low-CKAP2 group (n = 122) using the median expression value of CKAP2 as the cutoff point." (PMID 28522860, 2017). "In conclusion, our study suggests that CKAP2 acts as a functional oncogene in cervical carcinoma development and may exert its function by targeting FAK-ERK2 signaling pathway." (PMID 28522860, 2017).
cervical carcinoma (continued). "To investigate whether CKAP2 had a direct functional role in facilitating cell invasion in cervical carcinoma, we evaluated cancer cell migration and invasion through transwell assay after infection with pLKO.1-EGFP-CKAP2 shRNA." (PMID 28522860, 2017). "The exact pathways that CKAP2 may regulate in cervical carcinoma remain unclear." (PMID 28522860, 2017). "The expression of CKAP2 in the CIN III tissues was generally increased compared with that in adjacent tissues and decreased compared with that in cervical carcinoma tissues." (PMID 28522860, 2017). "Although CKAP2 was reported to be up-regulated in malignancies, the exact biologic functions of CKAP2 in cervical carcinoma have not been fully identified." (PMID 28522860, 2017). "VX-11e, an ERK2 inhibitor, inhibited the ERK2 activation in cervical carcinoma cells with either CKAP2 overexpression or not." (PMID 28522860, 2017).
colon cancer (3 papers, 2017 to 2025). "Importantly, our analysis also confirmed several well-characterized shared neoantigens, including AVEEVSLRK derived from an NPM1 frameshift mutation in AML, SLMEQIPHL from a CKAP2 frameshift mutation in colon cancer, and 37 private neoantigens now deposited in the IEDB database." (PMID 40672284, 2025). "A dataset (GSE14359, consisting of 5 pairs of adjacent tissues and colon cancer) in the GEO database revealed significant upregulation of CKAP2 expression in CRC." (PMID 39403723, 2024).
colorectal cancer (3 papers, 2013 to 2024). A primary or metastatic malignant neoplasm that affects the colon or rectum. "Similarly, for PYY-CKAP2 and SDCBP2-DAP3 gene pairs, up-regulation of CKAP2, DAP3 and down-regulation of PYY, SDCBP2 contribute to the reversal REO in colorectal cancer samples." (PMID 29378509, 2018).
gastric adenocarcinoma (2 papers, 2017 to 2025). "Previous study showed that 50% of gastric adenocarcinomas observed CKAP2 expression, but no protein was detected in normal mucosal cells." (PMID 28522860, 2017).
head and neck squamous cell carcinoma (2 papers, 2018 to 2023). A squamous cell carcinoma that arises from any of the following anatomic sites: lip and oral cavity, nasal cavity, paranasal sinuses, pharynx, larynx, and salivary glands. "CTD analysis showed that KNTC1, MCM2, CKAP2, RACGAP1, CCNB1 were associated with head and neck squamous cell carcinoma, necrosis, inflammation and hepatomegaly." (PMID 37480569, 2023). "Five genes (KNTC1, MCM2, CKAP2, RACGAP1, CCNB1) were found to be associated with head and neck squamous cell carcinoma, necrosis, inflammation and hepatomegaly." (PMID 37480569, 2023).